CD4 (CD4 molecule)
Diseases named in the same sentence as CD4 in open-access papers (continued):
Sharing a sentence is not in itself a finding about the gene and the disease.
Autoimmunity (continued). "Interestingly, cells in cluster 11 showed a distinct high expression of SMAD7 that in mice and humans have been associated with Th1 CD4+ T-cells involved in autoimmunity." (PMID 38287279, 2024). "The 24 T cell clusters spanned innate-like states and CD4+ and CD8+ adaptive lineages, including states implicated in autoimmunity, such as regulatory CD4+ T cells (Treg) (T-8 and T-9) and CXCL13- and IL21-expressing T follicular helper (TFH) and TPH cells (T-3 and T-7)." (PMID 37938773, 2023). "Additionally, this cluster upregulation in the DN1 stage was associated with enhanced proliferation of CD4+ cells mediating autoimmunity." (PMID 35328059, 2022). "While the typical percept is that autoimmunity can be pathogenic per se, the present proof indicates that ApoB-specific CD4+ T-helper cells have already been determined among subjects without clinical atherosclerosis and with atheroprotective characters mostly." (PMID 35663954, 2022). "While there is a clear association between autoimmunity and neutrophils, the contribution of NETs to the development of pathological CD4+ T cell responses has so far only been described through enhancement of the inflammatory microenvironment by stimulating innate immune cells." (PMID 35082281, 2022). "T1D associated SNP alleles in UBASH3A increase its expression in primary human CD4+ T cells and inhibit NF-κB signaling, resulting in reduced IL-2 production, which might increase the probability of initiating autoimmunity." (PMID 35812428, 2022). "This may enhance antigen presentation by APCs expressing risk HLA variants to their cognate CD4+ T cell, thereby initiating the process of autoimmunity." (PMID 36405681, 2022). "In addition, we observed that the number of CD4+FoxP3+ regulatory T cells, deficiencies in which will lead to severe autoimmunity, was also reduced in the Axl-/-Mertk-/- thymus." (PMID 35967387, 2022). "Interestingly, we found a significant increase of a rare population of double-positive CD4+CD8+ T cells linked to autoimmunity and chronic inflammatory diseases in pLn of both NIKβKO and WT MLDSTZ-treated mice." (PMID 35589698, 2022). "Furthermore, numerous studies also suggested that an altered balance of blood CXCR5+ CD4+ Tfh cell subsets was closely linked with autoimmunity." (PMID 36761174, 2022). "Integrins have been long implicated in recruitment of CD4+ T cells to the CNS during autoimmunity." (PMID 35250997, 2022). "Furthermore, the aged B cells tend to shift activated CD4+ T cells to Th17 phenotype, which is associated with autoimmune disorders." (PMID 34072224, 2021). "Thus, autoimmunity is understood as a competition of protective and pathogenic CD4+ T cells that both recognize (different) self-peptides from the same autoantigen." (PMID 33669769, 2021). "Human autoimmune conditions are also associated with cytotoxic CD4+ T cells." (PMID 34910940, 2021). "Interestingly, evidence suggests that the risk of autoimmunity in CVID is particularly increased in patients bearing a reduction in naïve CD4 cells, RTEs, naïve CD8 and Treg counts." (PMID 35058929, 2021). "The importance of posttranslationally created epitopes in the periphery for CD4 T cells in rheumatoid arthritis and celiac disease gave hints to mechanisms for how T cells escape both thymic deletion and peripheral T reg cells to go on to cause autoimmunity." (PMID 33095259, 2021). "NADPH oxidase deficiency could regulate Th lineage commitment to modulate autoimmunity, and superoxide provides a third signal for CD4 T cell effector responses." (PMID 34970267, 2021). "The mutation RhoA-G17V (a missense mutation leading to the change of the amino acid glycine on position 17 to valine) is common in CD4+ T-cells in lymphoma and is associated with autoimmunity, hyper-responsiveness of T-cells, and excessive TCR signaling via the Rho-GEF Vav1." (PMID 34359851, 2021). "Esrrg deficiency in Tregs leads to CD4+ T cell activation and autoimmunity in aged mice." (PMID 34156979, 2021).
Autoimmunity (continued). "Indeed, whereas deletion of mTOR in CD4+ T cells promoted CD4+ T cell differentiation to Tregs, loss of mTORC1 activity in Tregs impaired Tregs suppressive function and led to autoimmunity." (PMID 33802831, 2021). "In addition, the upregulation of this cluster in the DN1 stage has been associated with increased proliferation and survival of CD4+ T cells, which mediates the autoimmunity." (PMID 32852903, 2020). "In SLE, T-cells have: i) dysfunctional oxidative phosphorylation pathways which can reduce Treg counts and functional exhaustion; ii) enhanced glycolysis which increases Th17-associated autoimmunity; iii) reduced naïve CD4+T-cells and increased memory CD4+T-cells." (PMID 33361522, 2020). "IFN-γ is a well-known Th1 cell-produced cytokine, TNF-α is associated with a pro-inflammatory state and may also be secreted by Th1 cells, and IL-17A is a marker of CD4+ Th17 lymphocytes, which are associated with autoimmunity, inflammation, and chronic pain." (PMID 32497151, 2020). "Thus, the vigorous scurfy-like autoimmunity associated with CD25cKO mice appears to activate peripheral CD4+ Foxp3+ T cells, but these changes fail to prevent lethal disease." (PMID 30833563, 2019). "In addition to loss of naïve and regulatory T cells, an increase in T helper type 1 (TH1) and T follicular helper (TFH) CD4+ T cells have been described in association with autoimmunity in CVID." (PMID 31921101, 2019). "In addition, the reduction in the naïve CD4+ T cell numbers has been associated with an increased incidence of autoimmunity in patients with DGS." (PMID 30949166, 2019). "We identified a previously unknown innate-like pathogenic function of memory CD4+ T cells in autoimmunity." (PMID 30755603, 2019). "The observation that CD4+ T cells epigenetically altered with DNA methylation inhibitors could cause lupus-like autoimmunity in mice suggested that patients with idiopathic lupus might have similar epigenetically altered T cells." (PMID 30764520, 2019). "However, altered DNA methylation patterns in CD4+ T lymphocytes are caused by the environment–host interactions, and the epigenetically altered T cells are sufficient to cause lupus-like autoimmunity in animal models." (PMID 30764520, 2019). "Disrupted balance in the lineages of CD4+ T cell subsets, including pro-inflammatory T helper (Th) cells and anti-inflammatory regulatory T cells (Treg), is a primary pathogenic factor for developing autoimmunity." (PMID 30327657, 2018). "NRP1 may also function to suppress autoimmunity, as CD4+ loss of NRP1 in a mouse model of multiple sclerosis skews inflammatory populations to a TH-17 phenotype and reduces Treg populations, worsening autoimmune disease progression." (PMID 32914058, 2018). "The present study provides genetic evidence that JunB is required for Th17 cell differentiation: Junb-deficient CD4+ T cells are defective in differentiating into Th17 cells, and Junb-deficient mice are refractory to induction of the Th17 cell-dependent autoimmunity EAE." (PMID 29234109, 2017). "In addition, IL-27R-deficient mice show enhanced pro-inflammatory CD4+ T cell response and enhanced autoimmunity susceptibility and die following exposure to parasitic and bacterial infections due to severe immunopathology." (PMID 28993775, 2017). "Several animal and human studies have implicated CD4+ T helper 17 (Th17) cells and their downstream pathways in the pathogenesis of central nervous system (CNS) autoimmunity in multiple sclerosis (MS) and neuromyelitis optica spectrum disorders (NMOSD), challenging the traditional Th1-Th2 paradigm." (PMID 26941483, 2016). "Interestingly, the formation of different peptide–MHCII isomers has been associated with the activation of different sets of CD4+ T cells involved in autoimmunity; these links are discussed in the following section." (PMID 27534821, 2016).
Autoimmunity (continued). "Since B19 has been observed to establish a chronic infection, and to be linked with autoimmunity, it was of interest to explore whether such CD4+ CTLs could also emerge after B19 infection." (PMID 26246896, 2015). "Treg cell suppression by IL‐27 may lead to tissue damage by CD8+ T cells and/or the development of autoimmunity involving CD4+ T cells, and thus both can increase patient susceptibility toward exacerbation." (PMID 24994897, 2014). "We therefore hypothesized that transfer of wild-type CD4+ T cells might correct the increased susceptibility to autoimmunity in Lag-3−/− mice." (PMID 25122007, 2014). "In addition, our results indicate that LAG-3 expression on CD4+ T cells is critical for its regulatory role in Hg-induced autoimmunity since transfer of normal CD4+ T cells to LAG-3-deficient mice partially corrects their phenotype." (PMID 25122007, 2014). "However, a dysregulation in human CD4+ T cell polarization is associated with a variety of diseases, such as cancer, autoimmunity, and allergies." (PMID 25144736, 2014). "Understanding how recognition of insulin could endow pathogenic and/or regulatory roles to CD4+ T cells will help us understand how organ-specific autoimmunity develops and how it can be controlled." (PMID 25393309, 2014). "It stimulates a unique CD4+ inflammatory T-cell characterized by secretion of IL-17, tumor necrosis factor and IL-6, which are strongly associated with proinflammatory responses and severe autoimmunity." (PMID 23767933, 2013). "For example, the organism may be more likely to skew CD4+ T-cell reactivity to a Th17 phenotype, a response which has been implicated in autoimmunity." (PMID 24017968, 2013). "Conversely, CD4+CD25+ nTreg from wild-type mice transferred to IL-2-deficient mice fail to prevent autoimmunity and in vitro suppression activity is completely abrogated by selective blocking of the IL-2 receptor on nTreg during a coculture with responder T cells." (PMID 21647403, 2011). "Thus, our result is similar to the results of previous studies that suggest that both CD8+ Treg and CD4+ Treg can cause autoimmunity." (PMID 21364747, 2011). "On the other hand, short term treatment with high dose CTLA-4Ig (abatacept), which has been shown to have anti-inflammatory properties in arthritis, leads to a precipitous loss of CD4+CD25high regulatory T cells and, in some animal models, exacerbation of autoimmunity." (PMID 19046457, 2008). "Finally, all treatments led to a slight increase in the number of Foxp3+CD4+ T cells in tumor, a fact that highlights the inhibitory effect of P60 on Foxp3 activity rather the depleting cells that is associated with the development of autoimmunity." (PMID 39075226, 2025). "In addition to compromising Th17 differentiation, STAT1 GOF may also promote the differentiation of effector CD4 lineages linked to autoimmunity." (PMID 37275873, 2023). "Thus, SL induced inflammatory cytokines associated with autoimmunity in CD4+ TCs." (PMID 37132178, 2023). "Thus, homeostatic proliferation of neonatal and perinatally-generated CD4+ T cells coupled with the steep decline in thymic Tregs could create a window of increased susceptibility to autoimmunity post-puberty." (PMID 36533239, 2022). "However, naive CD4+ T-cell activation could result in autoimmunity, which causes the hyperstimulation of the immune system and increases the disease burden in a host." (PMID 35812417, 2022). "A previous study has reported the development of autoimmunity in elderly Hvcn1-deficient mice, which might be compatible with the preferential survival of T cells (particularly of the CD4+ subset) with lower antigen affinity, which are, therefore, more likely to include autoreactive T cells." (PMID 35472029, 2022).
Autoimmunity (continued). "In particular, miRNAs control the differentiation, survival, and activation of CD4+ T conventional (Tconv) cells, key players of the adaptive immunity, and regulate the physiological response to infections and the pathological loss of immune homeostasis in autoimmunity." (PMID 34778265, 2021). "We conclude that Clec4b expressed on CD4+ myeloid dendritic cells regulate the expansion of auto-reactive and potentially pathogenic T cells during an immune response, demonstrating an early checkpoint control mechanism to avoid autoimmunity leading to chronic inflammation." (PMID 32497089, 2020). "Moreover, adoptive transfer of CD4+ T cells derived from the syngeneic mice with AIP induced pancreatitis in the recipient RAG2-deficient mice, suggesting that autoreactive CD4+ T cells may induce autoimmunity in the pancreas." (PMID 32266154, 2020). "Interestingly, RXRA-mediated signaling enhances differentiation of functionally competent CD4+ regulatory T cells and potently inhibits the formation of CD4+ T helper 17 cells, the latter of which have been strongly implicated in various autoimmune pathologies, including MS." (PMID 31023360, 2019). "And if so, might autoimmunity associated with CD28null CD4 T cells be reversible?" (PMID 30984377, 2019). "Taking this into consideration, our results may suggest that reducing the availability of glutamine to the CD4+ cells might have beneficial effect on reducing T cells promoting autoimmunity by decreasing pathogenic CCR6 and CXCR3 bearing T cell and increasing regulatory T cells." (PMID 27467144, 2016). "In order to understand the pathogenic roles of CD4+ TEM cells in autoimmunity, we aimed to characterize the variation in their phenotypic and functional markers in a healthy population, and to identify whether these markers intersect with the genetic basis for autoimmunity." (PMID 24968232, 2014). "Thus, apart from excess BAFF directly affecting the activation and survival of autoreactive B cells, BAFF-dependent regulation of CD4+ T cell responses may also contribute to B cell hyperactivity and loss of tolerance in autoimmunity." (PMID 25010693, 2014). "It then follows that the ability of certain antigens such as measles virus to cause autoimmunity may be due to their ability, in conjunction with its ability to present antigen, to overstimulate CD4+ and/or CD8+ T cells of certain hosts beyond integrity of their immune system." (PMID 20046868, 2009). "Building on evidence from our group and others that Staphylococcus aureus and its peptidoglycan (PGN) promote autoimmunity, we investigated their contribution to anti-CD4 IgG in HIV." (PMID 41930968, 2026). "This concept is biologically plausible given that the highly polymorphic HLA region on chromosome 6 is strongly linked to autoimmunity, and that class I and class II alleles are essential for CD8+ and CD4+ T-cell activation, respectively." (PMID 41607457, 2026). "Here, we develop a mouse model to dissect the contribution of Id-driven T-B collaboration and show that chronic interaction between B cells and CD4+ T cells first leads to autoimmunity and later to the development of B (and T) cell lymphomas." (PMID 41741475, 2026). "In contrast to its role in autoimmunity, but consistent with its function in the presence of superantigens, we found that CD6 deficiency enhances CD4 T cell activation and CD4 T cell help to germinal center-dependent antiviral humoral responses." (PMID 39679790, 2025). "In autoimmunity and progressive thyroid dysfunction, we observed the rearrangement of N-glycan structures in Th cells, in opposite directions in the analyzed CD4+ pools." (PMID 41030447, 2025). "Stem-like CD4+ T cells have been identified in various immune contexts, including transplantation, autoimmunity, allergies, cancer, and chronic infections." (PMID 40634636, 2025).
Autoimmunity (continued). "In the literature, the CD4+ TH17 cells (characterized by IL-17 production) were reported to be actively involved in autoimmunity, anticancer immunity and transplant immunity." (PMID 41296449, 2025). "Regulatory T cells, as a specialized subset of CD4+ T cells, are best known for their role in preventing autoimmunity and maintaining immune homeostasis." (PMID 40631071, 2025). "Much of the focus for immunomodulation and metabolic reprogramming in autoimmunity has been on CD4+ T cells." (PMID 40493395, 2025). "Unlike naïve or TCM cells, which remain largely quiescent, antigen-specific stem-like CD4+ T cells in autoimmunity and transplantation are in a state of ongoing activation, continuously cycling to maintain self-renewal and generate effector progeny." (PMID 40634636, 2025). "In preclinical antigen‐specific immunotherapy models, Foxp3− CD4+ regulatory (Tr1) T cells have been shown to suppress CD8+ T cells during the development of autoimmunity." (PMID 40623940, 2025). "Among the different cells that aid in the maintenance of this tolerance, a specialised naturally occurring subset termed CD4+ regulatory T cells (Treg) are central for the prevention of autoimmunity." (PMID 41226379, 2025). "TCF1+ CD8+ and CD4+ T cells have been identified in a variety of settings, including chronic infections, autoimmunity, and cancer." (PMID 41256356, 2025). "Tregs, a distinct subset of T cells that make up 5% to 10% of the total CD4+ T cell population, play a crucial role in maintaining immune homeostasis and preventing autoimmunity." (PMID 41465903, 2025). "Our finding that Asn deprivation can ameliorate the severity of EAE, even after the priming of CNS-reactive CD4+ T cells, warrants further investigation in models of autoimmunity and immune dysregulation." (PMID 40661510, 2025). "By balancing self-renewal with effector differentiation, stem-like CD4+ T cells continue to replenish short-lived effector cells to sustain autoimmunity, transplant rejection, chronic infections, and allergic diseases." (PMID 40634636, 2025). "Naïve CD4+ T-cells undergo differentiation into various helper T-cell subsets, including Th17, Th1, and others, which are involved in autoimmunity, tissue inflammation, and other cellular processes." (PMID 41366351, 2025). "Methotrexate, Azathioprine, and Mycophenolate Mofetil are well-established in autoimmunity and offer predictable suppression of IL-2 and CD4 + T cells." (PMID 41057909, 2025). "CD4 T cells show less coordination of genes throughout the progression of autoimmunity preceding T1D." (PMID 40195977, 2025). "Previous studies have demonstrated that IL-6 regulates and promotes CD4+ T cell proliferation, thereby creating an exaggerated immune response and thus leading to autoimmunity and the development of SLE." (PMID 40429614, 2025). "Our data support the concept that circulating CD4 T cells targeting hepatic antigens are liver-derived autoreactive CD4 T cells and that their transcriptomic signature is imprinted by chronic antigen activation in the tissue during autoimmunity." (PMID 39880819, 2025). "T cells constitute another fundamental pillar determining the development of autoimmunity, with CD4+ T cells supporting B‐cell activation and both CD4+ and CD8+ T cells undertaking cytotoxic responses in affected tissues." (PMID 40534591, 2025). "T follicular helper (TFH) cells are the primary CD4+ T helper cell subset providing help to B cells for efficient antibody responses in vaccination, allergy, autoimmunity, and infectious diseases." (PMID 40359324, 2025). "Transfer of Treg cells (phenotypically CD4+CD25+Foxp3+) was able to block autoimmunity and the efficacy of adoptive T cell immunotherapy." (PMID 41256311, 2025). "CD4+ T helper (TH) cells and their subsets are critical for both protective antimicrobial immunity and driving pathological states such as autoimmunity and atopic disease." (PMID 40295428, 2025).